BCL2 (BCL2 apoptosis regulator)
Diseases named in the same sentence as BCL2 in open-access papers (continued):
Sharing a sentence is not in itself a finding about the gene and the disease.
cancer (continued). "Overexpression of anti-apoptotic Bcl-2 proteins in cancers tilts the balance towards cell survival." (PMID 26785948, 2016). "Therefore, the results are consistent with other EOs that downregulate Bcl-2 protein expression in different cancer cells to induce apoptosis as a relevant strategy to control cancer development and progression." (PMID 27491777, 2016). "The results showed that the two trichothecene mycotoxins induced the apoptosis of cancer cell HepG-2 via activation of caspase-9 and caspase-3, up-regulation of bax gene expression, down-regulation of bcl-2 gene expression, and disruption of the mitochondrial membrane potential of the HepG-2 cell." (PMID 27322225, 2016). "Although Bcl-2 family proteins were originally identified as key regulators of apoptosis, an impressive body of evidence has shown that pro-survival members of the Bcl-2 family, including Bcl-2, Bcl-XL, and Bcl-w, can also promote cell migration, invasion, and cancer metastasis." (PMID 26621844, 2016). "Within this context it is tempting to speculate whether an increased expression of miR-210 sensitizes cancer cells to Bcl-2 inhibitors." (PMID 27293381, 2016). "To unravel quantitative determinants underlying variability in anti-mitotic drug response, we constructed a single-cell dynamical Bcl-2 network model describing cell death control during mitotic arrest, and constrained the model using experimental data from four representative cancer cell lines." (PMID 27811996, 2016). "Aberrant activation of STAT3 signaling participates in the initiation, development and progression of human cancers via induction of STAT3 downstream genes that encode antiapoptotic proteins, cell cycle regulators and angiogenic factors such as Bcl-2, Cyclin D1 and VEGF." (PMID 27317769, 2016). "Several reports demonstrated that the ratio of pro-apoptotic to anti-apoptotic Bcl-2 proteins determines cell fate in cancer cells, whether cells can stay alive or die after treatment with apoptotic stimuli." (PMID 27138223, 2016). "B-cell lymphoma-2 (BCL2) protein is an anti-apoptotic molecule that is expressed at high levels in cancer cells including malignant plasma cell lines, and is related to cancer cell survival, early disease relapse and drug resistance." (PMID 27049723, 2016). "MiR-206 plays an important anti-cancer role via targeting c-Met, Bcl2, cyclinD1, and Sox9 in NSCLC." (PMID 27806334, 2016). "The Bcl-2 proteins modulate sensitivity of many types of cancer cells to chemotherapy." (PMID 26880588, 2016). "The anti-apoptotic Bcl-2 protein is overexpressed in a variety of cancers." (PMID 27578251, 2016). "Anti-apoptotic Bcl-2 proteins may provide survival benefits and induce therapy resistance in cancer cells." (PMID 27537525, 2016). "In addition, cancer cells tend to evade apoptosis by overexpressing anti-apoptotic proteins like Bcl-2 or down regulating pro-apoptotic proteins." (PMID 26734838, 2016). "The balance between the levels of Bcl-2 and Bax is critical for cancer cell survival." (PMID 26908448, 2016). "Furthermore, one study shows that isolated lectin (ricin) from the seed of R. communis induces apoptosis in the cancer cells by up-regulating pro-apoptotic protein (Bak) and down-regulating Bcl-2." (PMID 27405609, 2016). "However, several pathways modulate the apoptosis signaling and contribute to apoptosis resistance in cancers, such as Bcl-2 and Mcl-1 proteins, autophagy processes, aberrant nuclear export signaling, etc." (PMID 26923134, 2016). "In addition, the ratio of Bcl-2/Bax is an important indicator that can induce the apoptosis progress of cancer cells." (PMID 27271587, 2016).
cancer (continued). "As the overexpression of BCL2 is one of the major contributing factors to the development of multidrug resistance (MDR, a mechanism by which cancer cells resist structurally and mechanistically unrelated chemotherapeutic drugs), BCL2-specific miRNAs can also be used to treat MDR." (PMID 27512954, 2016). "Furthermore, IL-11 induced STAT3 phosphorylation and increased anti-apoptotic protein Bcl-2 and Survivin expression in cancer cells." (PMID 27922075, 2016). "Besides, we also found that Bufalin treatment increased the pro-apoptotic protein Bax, but decreased the anti-apoptotic protein Bcl-2 and Bcl-xl in the both cancer cell lines." (PMID 26758421, 2016). "Aberrant expression of Bcl-2 can help cancer cells by avoiding apoptosis." (PMID 28025559, 2016). "Overexpression of anti-apoptotic factor Bcl2 in cancer cells can be achieved by various post-transcriptional mechanisms, for example aberrant expression of miRNAs or increased protein phosphorylation and stabilization resulting in resistance toward cisplatin-induced cell death." (PMID 27105491, 2016). "BCL2 also serves as a regulator of cancer cell invasion and metastasis." (PMID 27244080, 2016). "modulates multidrug resistance by targeting BCL2 in human cancer cell lines." (PMID 32309578, 2016). "Its release is often blocked by overexpression of Bcl-2 in cancer cells." (PMID 27552933, 2016). "As the BCL2 gene encodes the anti-apoptotic protein BCL-2, the regulation in the expression of this target could be important in inducing apoptosis in cancer cells." (PMID 27011182, 2016). "Importantly, targeted anti-cancer therapies called BH3 mimetics have recently been developed to exploit this Bcl-2 dependency." (PMID 26833356, 2016). "Moreover, several anti-apoptotic proteins, such as Bcl-2 and Mcl-1, which are known to be crucial for cancer cell survival, are direct target genes of STAT3 and NFкB." (PMID 27539371, 2016). "In the present study we demonstrate cytotoxic effects of the modified compounds of 4-aryl-4-H chromenes family on these cancer cell lines and show that 3-NC, in addition to down regulation of inhibitor of apoptosis proteins (IAPs), functions through down regulation of Bcl2 and up regulation of Bax." (PMID 26074734, 2015). "In human breast MCF-7 cancer cells, our studies clearly show that stabilization of bcl2 protein by induction of wt53 protein by ·NO/·NO-derived species induces significant resistance to CPT, an important clinical drug for treatment of a wide variety of solid tumors." (PMID 26540186, 2015). "In this regard, inhibitor molecules of Bcl2 may represent a new class of therapeutic agents for cancer treatment." (PMID 26074734, 2015). "Therefore, it is imperative to develop novel gossypol derivatives with a higher binding affinity to Bcl‐2 proteins as well as good selectivity between normal and cancer cells with varying levels of Bcl-2 proteins." (PMID 25672487, 2015). "Therefore, it seems possible that Bcl-xL and Bcl-2 can mediate resistance to ABT-737 in some cancer cell types but that they are specifically targeted in others." (PMID 26447615, 2015). "Importantly, changes the ratio of pro-apoptosis Bcl-2 protein and anti-apoptosis Bcl-2 protein refer to chemotherapy resistance in many cancers." (PMID 26458953, 2015).
cancer (continued). "Although Bcl-2 promotes cell survival by two fully validated mechanisms, only the mechanism involving binding and inhibition of pro-apoptotic proteins is targeted for cancer treatment by the small-molecule BH3-mimetic ABT-263." (PMID 26720343, 2015). "Our results showed that the expression of these genes increased by 3.6 to 3.9 fold and 2.2 to 2.5 fold with regard to BAX and BAK1, respectively, whereas the Bcl-2 level decreased by 0.4 to 0.8 fold i.e., significant (p < 0.05), as compared to β-actin in both cancer cells." (PMID 25715710, 2015). "Thus, Bcl-2 appears an attractive target for the induction of apoptosis by PKC inhibition in cancer cells expressing oncogenic K-ras." (PMID 26041886, 2015). "Indeed, these compounds have been shown to trigger apoptosis through induced procaspase-3, -7, and poly (ADP-ribose) polymerase (PARP) cleavages and through regulation of Bcl expression (Bcl-2 and Bcl-xL) in human leukemia (HL-60) cancer cells." (PMID 26264004, 2015). "BCL-2 protein locating on intracellular membranes prevents apoptosis in response to various death inducing stimuli and its overexpression could promote cancer cell survival." (PMID 26132559, 2015). "In the same specimens the protein levels of Ubc9, MATα2 and Bcl-2 are all higher in cancer." (PMID 26416353, 2015). "Therefore, the proteolytic process regulating Bcl-2 stability appears one of the key players in sensitizing cancer cells expressing oncogenic ras to apoptosis." (PMID 26041886, 2015). "However, anti-apoptotic Bcl-2 family proteins such as Bcl-2, Bcl-xL, or Mcl-1 prevent the PTP opening and are associated with treatment resistance and progression in many types of cancer, including prostate cancer." (PMID 26252009, 2015). "Additionally, P38 MAPK triggers the activation of caspase-3, 9 and is also necessary for the phosphorylation of apoptosis-related proteins, including Bax, Bim and Bcl-2 in OA-treated cancer cells." (PMID 25946186, 2015). "BCL2 itself is considered as very attractive target of the therapy in many types of cancer." (PMID 24337970, 2015). "In addition, it has been shown that most cancers depend on more than one antiapoptotic Bcl-2 member for survival." (PMID 26117852, 2015). "In ESCC, BCL-2 plays its role in regulating cancer cell growth, especially in the early stage." (PMID 26132559, 2015). "Thus, the down-regulation (as well as inactivation) of anti-apoptotic Bcl-2 proteins can augment apoptosis, thereby increasing the efficacy of antitumor drugs in resistant cancer cells." (PMID 26370907, 2015). "Based on the immunohistochemistry analysis Bcl2 was up-regulated in the cancer control group." (PMID 26201720, 2015). "The BH3 motif of the anti-apoptotic Bcl-2 proteins is central to their function, and is the key to drug development strategies aimed at inhibiting anti-apoptotic Bcl-2 family members as a means to re-activate the intrinsic apoptotic pathway in cancer cells." (PMID 25784482, 2015). "Thus, blockade of Bcl-2 activity represents a novel and promising strategy for designing new class of anticancer drugs that can overcome the resistance of cancer cells to chemotherapy or radiation." (PMID 25823945, 2015). "Because cancer types with BCL2 and MCL1 amplification are more prone to inhibition of their respectively encoded proteins, we hypothesized that cancers with a significant frequency of BCL2L1 amplification would have greater dependency on BCL-XL for survival." (PMID 26134786, 2015). "SKOV3DDPovarian cancers cell expressed the highest bcl-2 levels." (PMID 25823945, 2015). "Interestingly, much of our current understanding about the regulation of MAC arose from studying cancer cells, which over express the sentinel protein Bcl-2." (PMID 26090338, 2015). "Either inhibiting the expression of Bcl-2 or enhancing the expression of Bax could be an effective approach for cancer therapy." (PMID 26307972, 2015).
cancer (continued). "PUMA is a general sensor of apoptotic stimuli and a promising drug target for cancer therapy, which induces apoptosis by activating the pro-apoptotic protein Bax through its interaction with anti-apoptotic Bcl-2 family members, including Bcl-2 and Mcl-1." (PMID 26147394, 2015). "The balance of Bcl-2 and Bax also plays an important role in the process of apoptosis in cancer cells, with the increase in Bcl-2 expression indicating the inhibition of apoptosis, and the decrease in Bax expression maintaining the proliferation of cancer cells." (PMID 26622820, 2015). "Finally, these compounds selectively killed MCL-1-dependent cancer cell lines (H929, H2110 and H23) and synergized with the BCL-2/BCL-XL inhibitor navitoclax to kill cell lines that rely on multiple BCL-2 family members for survival (BxPC-3, EJ-1, OPM-2)." (PMID 25590800, 2015). "The Bcl-2/Bax ratio is a reliable indicator of apoptosis in cancer cells." (PMID 25996383, 2015). "Disruption of Bcl2's antiapoptotic function via BH3 mimetics or the BH4 antagonist may represent attractive strategies for cancer treatment." (PMID 26682258, 2015). "Interestingly, several molecular and pharmacological agents capable of interfering with BCL-2 activity (such as BH3-mimetic compounds) are already used in cancer therapies." (PMID 26284195, 2015). "Transcriptional induction of Bcl2 is a major mechanism for apoptosis evasion in cancer cells." (PMID 26394044, 2015). "There is increasing evidence to suggest that Bcl-2 targeting therapy may be an effective treatment for many cancers." (PMID 26472348, 2015). "Thus, targeting the binding pocket of anti-apoptotic Bcl-2 proteins is a new and promising strategy for cancer therapy and drug discovery." (PMID 25672487, 2015). "In addition, Bcl-2 was significantly increased by 1 to 1.5 fold (p < 0.001) in both cancer cells, as compared to the plasma-treated group." (PMID 25715710, 2015). "For example, a cancer-promoting gene called BCL2 was more highly expressed in these cells." (PMID 26575290, 2015). "Here, we present evidence from cell and animal models to demonstrate that stabilization of Bcl-2 protein by phosphorylation at Serine 87 (pBcl-2-S87) via PXN-mediated ERK activation is responsible for cancer cell invasiveness and occurs via upregulation of MMP2 expression." (PMID 25826088, 2015). "B-cell lymphoma-2 (BCL-2) prevents apoptosis and its overexpression could promote cancer cell survival." (PMID 26132559, 2015). "A biochemical examination of PL-induced cell death indicated that it represses various anti-apoptotic proteins including B-cell CLL/lymphoma 2 (BCL2), baculoviral IAP repeat-containing 5 (also known as survivin) and X-linked inhibitor of apoptosis (XIAP) in cancer cells." (PMID 25984950, 2015). "Only Bcl-2 and serpin PI-9 proteins, which are confined to the cytoplasm of cancer cells, cannot." (PMID 26510188, 2015). "Moreover, low expression levels of Bax and caspase 3 and a high expression level of Bcl-2 were observed in the cancer control group." (PMID 25996383, 2015). "In addition, downregulation of Bcl-2 expression has been identified as a critical mechanism for cancer therapy." (PMID 26089933, 2015). "Based on the evidence that cancer types with BCL2 and MCL1 amplification are more prone to inhibition of their encoded proteins, we hypothesized that cancers with a significant frequency of BCL2L1 amplification are more dependent on BCL-XL for survival." (PMID 26134786, 2015). "Bcl-2 is an important anti-apoptotic protein which is expressed in several cancer types." (PMID 25601891, 2015).
cancer (continued). "Another important high-risk gene in cancer, BCL2, encoding the apoptosis regulator protein, Bcl-2, has also been reported to be expressed at increased levels in MG thymus in several studies, including one which showed that the expression levels of the Bcl2 family genes correlated with MG severity." (PMID 25118158, 2014). "BH3-exposed Bcl-2 might act similarly to BH3-only protein Bim to bind and inhibit other anti-apoptotic Bcl-2 proteins, such as Bcl-XL, as was demonstrated in cancer cells." (PMID 25182415, 2014). "Similarly, the co-crystal structure of Bcl-2 resulted in identification of a small molecule called ABT-199; a Bcl-2–selective inhibitor approved by the FDA for cancer therapy." (PMID 25268519, 2014). "In conclusion, the results from the present study suggest that emodin inhibits cancer cell growth via the regulation of Bcl-2/Bax and that the mitochondrial apoptosis pathway may be involved." (PMID 25187829, 2014). "This knowledge provides more insight into why some cancers are more sensitive to Bcl-2 targeting than others and will foster the clinical evaluation of Bcl-2-targeting strategies in cancer by avoiding severe on-target side effects in the development of healthy tissues." (PMID 24603326, 2014). "Bcl-2 or bcl-xL levels are elevated in a broad range of human cancers, indicating that these molecules may have a role in raising the apoptotic threshold in a broad spectrum of cancerous disorders." (PMID 25344863, 2014). "The Bcl-2 is an anti-apoptotic protein commonly over-expressed in many forms of cancers." (PMID 24566317, 2014). "Indeed, one or more of these anti-apoptotic Bcl-2 proteins is overexpressed in human cancers, resulting in resistance to chemotherapy and radiation." (PMID 24901320, 2014). "Additionally, ERKs inhibitor downregulated the expression of Bcl-2 and Bcl-xL, and ERKs/Bcl-2 signaling is believed to be a potential therapeutic target for cancer cells." (PMID 24738081, 2014). "The anti-apoptotic protein Bcl-2 is a well-known and attractive therapeutic target for cancer." (PMID 25268519, 2014). "Therefore, effect of all-trans retinoic acid (ATRA), which is known to deregulate Bcl-2 in many cancer cell types, was investigated in intact or DAC + SAHA treated cells." (PMID 25140197, 2014). "Indeed, Bcl-2 proteins have been regarded as important targets for anti-neoplastic drug development and Bcl-2 gen has been identified as over expressed in various cancers." (PMID 24393539, 2014). "Gene silencing capability of siRNA loaded magnetic MSNPs coated with polyethyleneimine effectively knock downed both exogenous enhanced green fluorescent protein (EGFP) gene and endogenous Bcl-2 gene with negligible cytotoxicity and released siRNA in cancer cells." (PMID 25071577, 2014). "According to this, the intracellularbalance between Bcl-2 and Bax maydetermine the prospect of cancer progressionand partly predict the clinical progression oftumoral diseases." (PMID 24381861, 2014). "Induction of apoptosis in Bcl-2-overexpressing cells requires sustained Ca2+ influx via activated channels (SOCs), and downregulation of these channels seems to be a key component of the protective action of Bcl-2 against apoptosis in hormone-insensitive cancer cells." (PMID 24493757, 2014). "Bcl-2 is an anti-apoptotic protein possessing an important role in various types of cancers." (PMID 24393539, 2014). "Therefore, great efforts have been made in order to target antiapoptotic Bcl-2 proteins aiming at cancer cell death induction." (PMID 25192188, 2014). "Furthermore, cancer cells are able to disrupt the balance between pro- (BCL-2, BCL-XL) and antiapoptotic factors (BAX, BIM, and PUMA)." (PMID 24999473, 2014).